RABEP1 (rabaptin, RAB GTPase binding effector protein 1)
Description:
Rab effector protein acting as linker between gamma-adaptin, RAB4A and RAB5A. Involved in endocytic membrane fusion and membrane trafficking of recycling endosomes. Involved in KCNH1 channels trafficking to and from the cell membrane. Forms a complex with RABGEF1 that stimulates RABGEF1-mediated nucleotide exchange on RAB5A. Mediates the traffic of PKD1:PKD2 complex from the endoplasmic reticulum through the Golgi to the cilium (By similarity).
Synonyms: RAB5EP; RABPT5; neurocrescin; rabaptin-5
Tractability: Small molecule: a structure with a bound ligand is known. PROTAC: ubiquitination databases record sites on it; its protein half-life has been measured.
Gene: Protein-coding gene on chromosome 17 (5,282,259 to 5,386,340, forward strand). Ensembl gene ENSG00000029725.
Subcellular location: Cytoplasm; Early endosome; Recycling endosome; Cytoplasmic vesicle
Subcellular location (Human Protein Atlas): Cytosol; Vesicles
Pathways (Reactome):
Vesicle-mediated transport: TBC/RABGAPs
Gene Ontology:
Molecular function: protein binding; protein domain specific binding; protein homodimerization activity; growth factor activity; GTPase activator activity
Biological process: vesicle-mediated transport; endocytosis; Golgi to plasma membrane transport; membrane fusion; protein localization to ciliary membrane; regulation of postsynaptic neurotransmitter receptor internalization; signal transduction
Cellular component: cytosol; endocytic vesicle; endosome; protein-containing complex; early endosome; early endosome membrane; cytoplasm; cytoplasmic vesicle; glutamatergic synapse; recycling endosome
Genetic constraint (gnomAD): Loss-of-function variants: 39 observed, 103.53 expected, observed/expected ratio (o/e) 0.38, 90% interval 0.29 to 0.49. The upper end of that interval is the gene's LOEUF score, 0.49, which puts it in group 2 of 6, group 1 being the genes least tolerant of losing a copy. Missense variants: 821 observed, 952.07 expected, observed/expected ratio (o/e) 0.86, 90% interval 0.81 to 0.91. Synonymous variants: 324 observed, 339.93 expected, observed/expected ratio (o/e) 0.95, 90% interval 0.87 to 1.04.
Cancer hallmarks: invasion and metastasis; suppression of growth (promotes)
Homologues: Orthologues: chimpanzee RABEP1 (99% identical), macaque RABEP1 (98% identical), pig RABEP1 (96% identical), mouse Rabep1 (96% identical), rat Rabep1 (96% identical), rabbit RABEP1 (95% identical), guinea pig RABEP1 (94% identical), dog RABEP1 (93% identical), tropical clawed frog rabep1 (78% identical), Caenorhabditis elegans rabn-5 (12% identical). Paralogues in human: RABEP2 (25% identical).
Diseases named in the same sentence as RABEP1 in open-access papers:
RABEP1 is named in the same sentence as 15 diseases in open-access papers, as found by Europe PMC text mining. Sharing a sentence is not in itself a finding about the gene and the disease. The quoted sentences say what the papers report.
breast carcinoma (3 papers, 2013 to 2020). "Increased expression of these genes also correlated with a decreased risk of breast cancer recurrence, although only four (RABEP1, PGR, SLC39A6 and FUT8) exhibited significant adjusted p-values." (PMID 23819905, 2013). "It has been reported that the overexpression of RABEP1, another biomarker of breast cancer, is predictive of reduced survival." (PMID 33193722, 2020).
Alzheimer disease (2 papers, 2018 to 2025). A progressive, neurodegenerative disease characterized by loss of function and death of nerve cells in several areas of the brain leading to loss of cognitive function such as memory and language. "We dissect distributional regulatory effects at established Alzheimer’s Disease (AD) risk genes including PITRM1, TMEM106B, and the CHRNE/SCIMP/RABEP1 cluster, revealing complex context-dependent regulatory architecture missed by linear analysis." (PMID 41377971, 2025). "At Alzheimer’s disease (AD) risk loci, qQTL analysis revealed complex regulatory architecture including variance effects at PITRM1, lower-quantile-specific effects at TMEM106B partially explained by APOE ε4 interactions, and coordinated epigenetic regulation at loci harboring CHRNE/SCIMP/RABEP1." (PMID 41377971, 2025).
pulmonary arterial hypertension (2 papers, 2022 to 2024). Pulmonary arterial hypertension (PAH) is a group of diseases characterized by mean pulmonary artery pressure >20 mmHg and elevated pulmonary arterial resistance leading to right heart failure. "RABEP1 is involved in vesicular transport and autophagy and one study has found its increased expression in heart and lung tissue to be associated pulmonary arterial hypertension in mice." (PMID 39217505, 2024).
dyslipidemia (1 paper, 2025). "Moreover, several of the loci implicated in our analysis, such as those near SLC13A5, RABEP1, and WSCD1, overlap functionally with pathways previously associated with adiposity, dyslipidemia, and glucose regulation." (PMID 40429953, 2025).
neural tumors (1 paper, 2025). "Overall, by comparing to PA, we identified subtype-specific pathways in neural tumors: PAK signaling (PTPRD and PDGFRB) in GBM, regulation of CFTR activity pathway (PPP2R1A, RABEP1) in MBL, and ERK signaling (IRS4 and ATM) in NBL." (PMID 40768543, 2025).
primary immunodeficiencies (1 paper, 2018). "WES revealed heterogeneous genetic background among CVID patients with tumors, identifying gene variants associated with primary immunodeficiencies (such as CTLA4, PIK3CD, PMS2) and/or increased cancer susceptibility (including BRCA1, RABEP1, EP300, KDM5A)." (PMID 30723478, 2018).
tumour (5 papers, 2013 to 2023). "In tumor samples gene expression analysis showed no significant variation between WT and heterozygous KIT mutated tumors, with a high inner variability in ANXA8, FBN1, GALNTL4, MFAP5 and RABEP1 expression, which was partly reduced by separating exon 9 and exon 11 mutated tumors." (PMID 23593401, 2013).
RABEP1 also shares sentences with these, for which no sentence is quoted: cancer (4 papers); breast tumours (2); infection (2); cerebral malaria (1); chronic myelomonocytic leukemia (1); multiple system atrophy (1); pertussis (1); subarachnoid haemorrhage (1).